COPB2 (coat protein complex I subunit beta 2)
Diseases named in the same sentence as COPB2 in open-access papers (continued):
Sharing a sentence is not in itself a finding about the gene and the disease.
glioma (6 papers, 2020 to 2022). A benign or malignant brain and spinal cord tumor that arises from glial cells (astrocytes, oligodendrocytes, ependymal cells). "Similar to a study on glioma, a significant association was found between COPB2 expression and both CD8+ and CD4+TILs in cSCC tissues." (PMID 35454945, 2022). "For example, high COPB2 expression was closely linked to higher immune cell infiltration in gliomas." (PMID 33960680, 2021). "Thus, this research aimed to reveal the association between COPB2 and glioma and explore the potential prognostic value of COPB2 in patients with glioma based on The Cancer Genome Atlas (TCGA), Oncomine, and the Gene Expression Omnibus (GEO) databases." (PMID 31710183, 2020). "Gene set enrichment analysis (GSEA) showed that some immune‐related pathways and other signaling pathways in cancer were associated with the COPB2 high expression phenotype, shedding light on the molecular mechanisms underlying the onset and progression of glioma." (PMID 31710183, 2020). "In glioma, COPB2 expression was also correlated with the accumulation of Tregs, neutrophils, and MDSCs, which are considered mediators of the immunosuppressive microenvironment in various types of cancers." (PMID 35454945, 2022). "According to a previous study, there is a significant association between COPB2 expression and both MHC I and MHC II in gliomas." (PMID 35454945, 2022). "In gliomas, COPB2 has been reported to be an important factor in the regulation of the immune microenvironment, and its high expression is related to adverse outcomes." (PMID 33824874, 2021). "In glioma, 675 glioma patients with COPB2 expression profile data were obtained from TCGA COPB2 is significantly upregulated in tumor tissues relative to nontumor tissues (P < .001)." (PMID 31710183, 2020). "As far as we are aware, at present, this is the first study to explore the prognostic value of COPB2 in patients with glioma." (PMID 31710183, 2020). "To investigate the predictive implications of COPB2 in glioma prognosis, we analyzed COPB2 expression and the OS in the TCGA database." (PMID 31710183, 2020). "COPB2 was highly expressed in gliomas and high COPB2 expression correlated with shorter overall survival time and several poor clinical prognostic variables." (PMID 31710183, 2020). "Oncomine, GEO, and The Cancer Genome Atlas databases were used to examine the COPB2 transcript levels in glioma tissues." (PMID 31710183, 2020). "Gene expression profiles with clinical information from low‐grade glioma and glioblastoma (GBM) projects were analyzed for associations between COPB2 expression and clinicopathologic characteristics." (PMID 31710183, 2020). "In the present study, we demonstrated that the overexpression of COPB2 in glioma was correlated with advanced clinicopathologic characteristics and predicts worse outcomes." (PMID 31710183, 2020). "GSEA was utilized to recognize signaling pathways involved in glioma between low and high COPB2 expression cohorts." (PMID 31710183, 2020). "This study revealed that COPB2 expression was upregulated in glioma samples and was related to adverse outcomes." (PMID 31710183, 2020). "In addition, certain immune reaction-related pathways, such as antigen processing and presentation, B-cell receptor signaling pathway, and T-cell receptor signaling pathway, were also found to be significant pathways responsible for COPB2 increase in glioma." (PMID 35454945, 2022). "In addition, COPB2’s high expression in patients with glioma was further validated in the TCGA and GEO databases." (PMID 31710183, 2020). "As many signaling pathways contribute to tumor initiation and progression, the poor prognosis of COPB2‐high may be related to the numerous signaling pathways activated in glioma." (PMID 31710183, 2020). "We also found that COPB2 may represent an important factor in the immunomodulation of the glioma immune microenvironment." (PMID 31710183, 2020).
glioma (continued). "The results indicated increased transcript levels of COPB2 in glioma." (PMID 31710183, 2020). "Glioma patients with COPB2‐high had a worse prognosis than that with COPB2‐low (P < .001)." (PMID 31710183, 2020). "Therefore, taken together, COPB2 may act as a potential biomarker of prognosis and immunotherapeutic target for glioma." (PMID 31710183, 2020). "Yet, the clinical significance of COPB2 in glioma remains unclear." (PMID 31710183, 2020). "COPB2 may be a potential prognostic biomarker and an immunotherapeutic target for glioma." (PMID 31710183, 2020). "The results indicated that COPB2 was significantly overexpressed in glioma tissues compared with nontumor tissues and that high COPB2 expression was correlated with higher WHO grade, shorter overall survival (OS) time, and several poor clinical prognostic variables." (PMID 31710183, 2020).
colon cancer (5 papers, 2020 to 2022). "The underlying molecular mechanism of COPB2 was assessed in breast and colon cancers, OV, and UCEC with regard to total and phosphorylated protein levels." (PMID 34676262, 2021). "Moreover, COPB2 can induce G0/G1 and G2/S phase arrest in various types of cancers; the regulatory action of COPB2 on the contributors of cell-cycle progressions, such as cyclin A, p21, and p16, was indicated as the underlying molecular mechanism of cell-cycle arrest in human colon cancer." (PMID 35454945, 2022). "In several cancer types, COPB2 expression is dysregulated, such as breast, bile duct, and colon cancers." (PMID 34676262, 2021). "We have previously reported that COPB2 is highly expressed in human colon cancer tissue and cells, and its increased expression is positively correlated with increased pathological grading." (PMID 33211699, 2020). "In this study, we altered the expression of COPB2 in CRC cells to better characterize the roles of COPB2 in colon cancer." (PMID 33211699, 2020). "Furthermore, it was reported that COPB2 affected the cell cycle by regulating p21 and cyclin A, promoted the proliferation of colon cancer cells ultimately." (PMID 35600351, 2022). "This study reveals that COPB2 is essential for the proliferation and apoptosis of colon cancer indicating that it may serve as a potential target for the treatment of CRC." (PMID 33211699, 2020).
colorectal cancer (5 papers, 2017 to 2024). A primary or metastatic malignant neoplasm that affects the colon or rectum. "COPB2 gene silencing inhibits colorectal cancer cell proliferation and induces apoptosis via the JNK/c-Jun signaling pathway." (PMID 35715770, 2022). "The expression of COPB2 was correlated with the pathologic stage of colorectal cancer patients, but incorrelated to age and gender." (PMID 33211699, 2020). "TCGA database was used to confirm the correlation between COPB2 and clinical parameters of colorectal cancer." (PMID 33211699, 2020). "To further investigate the role of COPB2 gene in the development of colorectal cancer, we suppressed the expression of COPB2 via lentivirus-medicated RNAi transduction in CRC RKO and HCT116 cells." (PMID 33211699, 2020). "The results confirmed that COPB2 was closely related to the differentiation degree, tumor stages and a shorter survival time of colorectal cancer." (PMID 33211699, 2020). "Moreover, the down-regulation of COPB2 by microRNA-4461 inhibits tumorigenesis derived by EVs in colorectal cancer." (PMID 39661666, 2024). "The relationship between COPB2 gene and colorectal cancer is an interesting topic." (PMID 33211699, 2020). "Is COPB2 also related to the occurrence and development of colorectal cancer?" (PMID 33211699, 2020). "Expression of COPB2 in colorectal cancer and paracancerous tissue by IHC staining." (PMID 33211699, 2020). "Then, we seriously suspected that COPB2 may be an oncogene in the development of colorectal cancer." (PMID 33211699, 2020). "The result suggested that COPB2 may be a oncogene in colorectal cancer." (PMID 33211699, 2020). "We confirm COPB2 as SLP in knock down experiments on pancreas and colorectal cancer cell lines." (PMID 28415695, 2017). "In addition, there is a significant difference regarding the reduction of living cells after COPB2 knock down in the heterozygous colorectal cancer cell line DLD-1, compared to negative control." (PMID 28415695, 2017).
cholangiocellular carcinoma (4 papers, 2020 to 2021). "Downregulation of COPB2 could inhibit the growth of human cholangiocellular carcinoma cells." (PMID 33824874, 2021). "COPB2 also reportedly promotes lung cancer cell proliferation and tumorigenesis by upregulating YAP1 expression, and silencing COBP2 significantly inhibits cell proliferation and induces apoptosis in cholangiocellular carcinomas." (PMID 31926110, 2020).
COVID-19 (4 papers, 2023 to 2024). A disease caused by infection with severe acute respiratory syndrome coronavirus 2. "High levels of COPB2 within EVs upon hospital admission were associated with patients who progressed with mild COVID-19 symptoms in comparison to those with severe COVID-19 disease outcomes and healthy controls." (PMID 38398672, 2024). "For COVID-19, early biomarkers, such as those linked to EV proteins, blood coagulation related markers, and liver damage, have been identified, with EV coatomer protein complex subunit beta 2 (COPB2) having the greatest predictive value for severe disease." (PMID 36983995, 2023). "COPB2 was proposed as an early predictor of COVID-19 severity, and its level in circulating extracellular vesicles (EVs) is substantially higher in patients with mild infection symptoms compared to those with severe infection." (PMID 38674024, 2024). "It was determined that COPB2 protein, a subunit of the Golgi coat complex subunit Beta 2 found inside EVs, served as a predictive biomarker for COVID-19 disease severity." (PMID 38398672, 2024). "COPB2 was proposed as an early predictor of COVID-19 severity." (PMID 38674024, 2024).
developmental delay (3 papers, 2024 to 2025). "Loss of COPB2 gene function has been identified as the cause of a rare genetic disorder characterized by coatopathy, osteoporosis, and developmental delay." (PMID 38665758, 2024). "Individuals carrying COPB2 mutations exhibit various clinical manifestations, such as osteoporosis, which weakens bones and increases fracture risk, as well as developmental delay or impaired nervous systems." (PMID 38665758, 2024). "In addition to MCPH19, COPB2 mutations also cause juvenile osteoporosis, and developmental delay." (PMID 40978486, 2025).
glioblastoma (3 papers, 2020 to 2022). The most malignant astrocytic tumor (WHO grade IV). "In cancer, COPB2 is highly expressed in glioblastomas and hepatocellular carcinomas, resulting in a worse overall survival." (PMID 35909471, 2022).
hepatocellular carcinoma (3 papers, 2021 to 2025). A malignant tumor that arises from hepatocytes. "This study is aimed at investigating the expression, underlying biological function, and clinical significance of coatomer protein complex subunit beta 2 (COPB2) in hepatocellular carcinoma (HCC)." (PMID 33824874, 2021).
lung carcinoma (3 papers, 2020 to 2021). "A previous study indicated that the expression of COPB2 is associated with cell growth, apoptosis, migration and invasion, functioning through a miR-216a manner, in lung cancer." (PMID 34150620, 2021). "Recently, numerous reports have indicated that COPB2 is abnormally expressed in colorectal cancer (CRC), cholangiocellular carcinoma and lung cancer." (PMID 34150620, 2021). "Moreover, miR4461 and miR335 were found to regulate COPB2 expression, which subsequently inhibited cell growth in CRC and lung cancer cells." (PMID 34150620, 2021).
lymph node metastasis (3 papers, 2019 to 2022). "In our validated cohort, we found that higher COPB2 expression group had more lymph node metastasis (P = 0.033) and younger age (P = 0.007) than lower COPB2 expression group." (PMID 31119859, 2019). "Up‐regulated expression of COPB2 was correlated with lymph node metastasis (LNM) and oestrogen receptor (ER) in the TCGA cohort and a high level of COPB2 was associated with age and lymph node metastasis in the validated cohort." (PMID 31119859, 2019). "The human oestrogen receptor (ER) expression (P = 0.038) and lymph node metastasis (P = 0.035) were significantly related to the expression of COPB2." (PMID 31119859, 2019).
acute myeloid leukemia (2 papers, 2021). Acute myeloid leukemia (AML) is a group of neoplasms arising from precursor cells committed to the myeloid cell-line differentiation. "Subsequently, the differences in COPB2 expression were assessed between normal tissues and DLBC (lymphoid neoplasm diffuse large B cell lymphoma) (P < 0.05), LGG (brain lower grade glioma), LAML (acute myeloid leukemia), SKCM (skin cutaneous melanoma), and THYM (thymoma) tissues." (PMID 34676262, 2021).
cutaneous squamous cell carcinoma (2 papers, 2022 to 2025). "The present study aimed to evaluate the effect of COPB2 expression on cutaneous squamous cell carcinoma (cSCC) pathogenesis." (PMID 35454945, 2022).
mesothelioma (2 papers, 2019 to 2020). A usually malignant and aggressive neoplasm of the mesothelium which is often associated with exposure to asbestos. "Likewise, Sudo et al19 found the involvement of COPA and COPB2 during cellular growth as well as during apoptosis of mesothelioma cells in vitro." (PMID 31119859, 2019).
microcephaly (2 papers, 2018 to 2025). A congenital or acquired developmental disorder in which the circumference of the head is smaller than normal for the person's age and sex. "For example, human patients homozygous for a variant in COPB2 exhibited microcephaly, whereas a mouse model required the Copb2 variant allele to be combined with a Copb2 null allele to cause brain malformations." (PMID 30355621, 2018).
ovarian carcinoma (2 papers, 2012 to 2021). A malignant neoplasm originating from the surface ovarian epithelium. "A meta-analysis also identified COPB2 as one of four downstream targets of PKCι, which we have shown to contribute to poor prognosis through loss of apical-basal polarity and overexpression of cyclin E in ovarian cancer." (PMID 22745748, 2012).
bladder cancer (1 paper, 2025). "First, we performed Co‐IP assay to confirm endogenous binding of COPA, COPB2, COPB1, and COPG in bladder cancer cells." (PMID 40112217, 2025).
brain malformation (1 paper, 2025). "The R254C homozygous mutation in COPB2 causes primary autosomal recessive microcephaly 19 (MCPH19), a congenital brain malformation." (PMID 40978486, 2025).
colon adenocarcinoma (1 paper, 2021). "It is interesting to note that COPB2 expression correlated with the number of cancer-associated fibroblasts in certain tumors, such as cervical and endocervical cancers and colon adenocarcinomas." (PMID 34676262, 2021).
endometrial cancer (1 paper, 2021). Primary or metastatic malignant neoplasm involving the endometrium (mucous membrane that lines the endometrial cavity). "It was found that mutations of the COPB2 protein in kidney and endometrial cancers exhibited a significant impact on patient prognosis." (PMID 34676262, 2021).
esophageal cancer (1 paper, 2026). A primary or metastatic malignant neoplasm involving the esophagus. "Gene amplification, most notably of COPB2, was the most frequent alteration and was associated with poor survival in bladder and esophageal cancers." (PMID 41751842, 2026).
kidney cancer (1 paper, 2021). Primary or metastatic malignant neoplasm involving the kidney. "Conversely, patients with COPB2 alterations in kidney cancer exhibited worse prognosis in terms of OS (P = 2.49e − 7), DFS (P = 1.74e − 8), PFS (P = 1.558e − 5), and DSS (P = 8.62e − 8)." (PMID 34676262, 2021).
liver cancer (1 paper, 2021). An epithelial or non-epithelial malignant neoplasm that arises from the liver. "In a recent liver cancer study, the database of specific patient data was used and the data demonstrated that patients with high COPB2 expression exhibited a poorer prognosis." (PMID 34676262, 2021).
pancreatic cancer (1 paper, 2017). "Given the role of COPB2 in apoptosis signaling, as shown by our experiments, we suspect that the simultaneous inhibition of COPB2 and KRAS in pancreatic cancer cells will be more effective than COPB2 silencing alone." (PMID 28415695, 2017).
stomach adenocarcinoma (1 paper, 2021). "Results indicated increased expression of COPB2 in primary tumor of the stomach adenocarcinoma (STAD) patients." (PMID 34150620, 2021).
triple-negative breast carcinoma (1 paper, 2025). An invasive breast carcinoma which is negative for expression of estrogen receptor (ER), progesterone receptor (PR), and human epidermal growth factor receptor 2 (HER2). "In addition, COPB2 has been reported to promote proliferation in triple-negative breast cancer." (PMID 40657358, 2025).
vascular tumor (1 paper, 2025). "Multivariate analysis identified COPB2 combined with YAP1 expression, vascular tumor thrombus, and TNM staging as independent risk factors." (PMID 40191726, 2025).
viral infection (1 paper, 2021). "In this context, EV COPB2 expression in viral infection might reflect the host factors that stimulate or restrict viral replication." (PMID 34122778, 2021).